CXCL10 (C-X-C motif chemokine ligand 10)
Diseases named in the same sentence as CXCL10 in open-access papers (continued):
Sharing a sentence is not in itself a finding about the gene and the disease.
bacteremia (9 papers, 2010 to 2025). "We have seen CXCL10 upregulated in Bacteremia and individuals in the Bacteremia group whose transcriptomic profiles indicated a transition towards septic shock." (PMID 38817614, 2024). "The investigators postulated that CXCL10 regulates beneficial myeloid cell recruitment during bacterial sepsis in neonatal mice." (PMID 24890566, 2014). "Interestingly, CXCL10 was significantly upregulated (linear FC of 2.1) only when comparing Cluster 3 against Cluster 1, possibly corresponding to the contribution of individuals with bacteremia whose transcriptomic profiles indicated a transition towards septic shock." (PMID 38817614, 2024). "For example, CXCL10, a chemokine that recruits T cells, natural killer cells, and monocytes, was found upregulated in neonates with bacteremia but not in those with septic shock." (PMID 40927580, 2025). "However, the functional importance of CXCL10 in facilitating the pathogenesis of severe bacterial sepsis had not been directly examined." (PMID 24890566, 2014).
chronic hepatitis B (9 papers, 2014 to 2025). "A previous study showed that rs56061981, polymorphism of CXCL10 promoter, modifies the binding affinity of nuclear protein and regulates CXCL10 expression, which is related to susceptibility to disease progression in chronic hepatitis B infection." (PMID 26339796, 2015). "These cases suggest that the increase in the serum levels of CXCL9, CXCL10, CXCL11, and CXCL13 were associated with attaining an HBsAg loss in children with chronic hepatitis B." (PMID 37206604, 2020).
cryptosporidiosis (9 papers, 2012 to 2024). Intestinal infection with organisms of the genus Cryptosporidium. "Studies in human intestinal ECs show that chemokines such as CCL-5, CXCL-8, and CXCL-10 are upregulated in Cryptosporidium infection, and CXCL-8 is detectable in the stool samples of children infected with cryptosporidiosis." (PMID 37110479, 2023). "In HIV/AIDS patients with active cryptosporidiosis, infected epithelial cells express high levels of the chemokine, CXCL10, and expression levels correlate with the parasite burden." (PMID 36504775, 2022). "Since CXCL10 increases the rate of HIV replication in vitro, elevated CXCL10 in cryptosporidiosis may contribute to enhanced destruction of CD4+ T cells due to HIV infection." (PMID 36504775, 2022).
diabetic retinopathy (9 papers, 2008 to 2025). "Concentrations of CCL8, CCL2, CXCL8 and CXCL10 may be associated with diabetic eye disease, especially in diabetic retinopathy and diabetic macular edema." (PMID 38790059, 2024).
idiopathic pulmonary fibrosis (9 papers, 2016 to 2026). Idiopathic pulmonary fibrosis (IPF) is a nonneoplastic pulmonary disease that is characterized by the formation of scar tissue within the lungs in the absence of any known cause. "It has been reported that in HTLV-1 positive cryptogenic fibrosing alveolitis (CFA) patients, a chronic inflammatory interstitial lung disease, the BALF levels of CCL3 and CXCL10, T cell chemoattractants and activators, are higher than those of without HTLV-1 infection." (PMID 32231656, 2020).
ischemic stroke (9 papers, 2015 to 2025). A stroke disorder caused by obstruction of blood flow to the brain, due to thrombotic (local blood clot formation) or embolic (due to a blood clot or other material traveling from another site) event. "We found that higher CXCL10 plasma levels correlate with unfavourable immediate and long-term functional outcomes and a higher fatality rate within 5 years of an ischemic stroke." (PMID 38861234, 2025). "In our photothromobotic ischemic stroke model, the upregulation of Cxcl10 and Ccl2 was particularly pronounced in the old mice." (PMID 40867143, 2025). "An interaction effect of ischemic stroke and aging was observed for Cxcl10 and Ccl2, with p-values of 0.079 and 0.075, respectively, but not for Tnfa." (PMID 40867143, 2025). "This is supported by human postmortem analyses, revealing up-regulation of CXCL10 in the brains of ischemic stroke patients." (PMID 38861234, 2025). "In this study, we demonstrated that among the inflammatory cytokines upregulated in the infarct region of the mouse photothrombotic ischemic stroke model, the induction levels of Cxcl10, Ccl2, and Tnfa mRNAs were substantially higher in the old mice than in the young ones." (PMID 40867143, 2025). "Remarkably, defective VDR signaling in microglia/macrophages resulted in pronounced upregulation of chemokines after acute ischemic stroke, including CXCL10 and CCL2, together with aggravated disruption of the BBB and infiltration of peripheral T cells and monocytes/macrophages." (PMID 36890539, 2023). "It was identified that CXCL10 and IL-6 may have important roles in the progression of ischemic stroke and thus may be used as specific therapeutic molecular targets." (PMID 25333814, 2015). "In the present study, CXCL10 acted as a hub node in the network suggesting this gene has an important role in ischemic stroke development and may be used as a specific therapeutic molecular target in the treatment of ischemic stroke." (PMID 25333814, 2015). "Ischemic stroke induces the release of different chemokines such as CCL-2, CCL-3, CCL-4, CCL7, CCL-11, CXCL-1, CXCL10, from the ischemic tissue." (PMID 30584250, 2018). "In conclusion, the results suggest that CXCL10 and IL-6 have important roles in the occurrence and progression of MCAO-induced ischemic stroke." (PMID 25333814, 2015).
leishmaniasis (9 papers, 2012 to 2025). Infectious disease that is transmitted through the bite of hematophagous female phlebotomine sand flies. "In this study, the ROC curve analysis of the GSE55664 dataset (early vs. late phase) identified two significant hub genes, GBP1 and CXCL10, highlighting their potential as biomarkers for early leishmaniasis diagnosis, consistent with previous studies." (PMID 39342024, 2024). "The results of KEGG pathway analysis showed that the functions of CXCL10 and its neighboring genes were mainly enriched in the NF-kappaB signaling pathway, allograft rejection, primary immunodeficiency and leishmaniasis." (PMID 33345267, 2021).
metastatic tumors (9 papers, 2018 to 2025). "The high levels of CXCL10 in tumor tissues are in line with a previous report that showed CXCL10 upregulation in metastatic tumors and demonstrated its functional role in tumor cell migration and invasion." (PMID 32503584, 2020). "The CXCR3/CXCL10 axis seems to be involved in metastatic disease in several tumour types." (PMID 39146303, 2024). "Some cytokines and chemokines, such as C-X-C motif chemokine ligand 10 (CXCL10), C-C motif chemokine ligand 4 (CCL4), CCL17, and IL-8, are also highly expressed in the CSF of metastatic tumors." (PMID 36531024, 2022).
microcephaly (9 papers, 2018 to 2023). A congenital or acquired developmental disorder in which the circumference of the head is smaller than normal for the person's age and sex. "In the infants evaluated here, an association was found between the presence of at least one G allele for the rs4508917 SNP in the CXCL10 gene and the occurrence of microcephaly." (PMID 36859461, 2023). "The SNP rs4508917 in the CXCL10 gene was also associated with the occurrence of microcephaly when the C-MICRO group and the C-CT group were compared, showing a higher frequency and association of G allele in children with CZS." (PMID 36859461, 2023). "Interestingly, the levels of chemokines associated with microcephaly in humans, including CCL2 and CXCL10, specifically increased in embryos harboring ZIKV in the embryo brains." (PMID 31212905, 2019). "A polyfunctional immune activation associated with increased CCL2, CXCL10, IL-6, IL-8, VEGF, and G-CSF levels but decreased levels of IL-13 was also described in the amniotic fluid of ZIKV-positive pregnant women whose infants had microcephaly." (PMID 29768624, 2018). "In this study, TREM1 rs2234246 and IL4 rs224325 in mothers infected with ZIKV during pregnancy was found to be associated with the occurrence of CZS microcephaly and the SNP CXCL10 rs4508917 and CXCL8 rs4073 in their children with presence of CZS microcephaly." (PMID 36859461, 2023). "We demonstrated that IFN-α, CXCL10, and CXCL9 levels were significantly higher in CSF samples obtained from ZIKV-induced microcephaly cases, compared to healthy control subjects." (PMID 31474994, 2019). "From ZIKV-confirmed infant microcephaly cases, we detected a similar profile characterized by the presence of IFN-α, CXCL10, and CXCL9 in cerebrospinal fluid (CSF) samples collected after birth, evidencing a sustained CNS inflammation." (PMID 31474994, 2019). "When cases (with or without microcephaly) were compared with controls, IL-1α, IL-7, IP10 (CXCL10), and GCSF were significantly higher among controls." (PMID 33875756, 2021). "Moreover, the amniotic fluid from ZIKV-positive pregnant women whose children presented microcephaly revealed exceedingly high levels of cytokines and growth factors: IL-15, CCL11, CXCL10, G-CSF, IL-10, IL-1β, TNF-α, CXCL8, CCL2 and CCL5." (PMID 34357089, 2021). "Finally, cerebrospinal fluid from infants with ZIKV-induced microcephaly showed a maintenance of the inflammatory environment by the presence of IFN-α, CXCL10 and CXCL9 after birth." (PMID 34357089, 2021). "Interestingly, consistent with the in vitro results, two CXC chemokine ligands were found at significantly higher levels in the CSF samples from microcephaly cases: CXCL9 and CXCL10 (p = 0.028, and p = 0.0003, respectively)." (PMID 31474994, 2019). "In addition, it was reported that there were increased levels of CXCL10 and CCL2, IL-6, IL-8, VEGF, and G-CSF in the amniotic fluid of ZIKV-positive pregnant women with neonatal microcephaly." (PMID 31474994, 2019). "When only cases without microcephaly were compared with controls, IL-1α and IP10 (CXCL10) were significantly higher among controls." (PMID 33875756, 2021).
neuropathy (9 papers, 2009 to 2025). A disorder affecting the nervous system that manifests with pain, tingling, numbness, and/or muscle weakness. "Among these, CXCL10 levels are significantly elevated in T2DM patients with neuropathy." (PMID 41302503, 2025). "Therefore, in our opinion, the modulation of CXCR3/CXCL10 signaling can bring satisfactory pain relief in neuropathy." (PMID 37570736, 2023). "Several studies also suggest a key role of CXCL10/CXCR3 signaling in neuropathy." (PMID 35962398, 2022). "It is important to note, however, that chemokines, such as CXCL10, have multiple effects in virus-induced neuropathy, since on the one hand, it has been reported to be neuroprotective, whereas on the other hand, it exerts neuro-pathogenic potential by triggering apoptosis." (PMID 33799906, 2021). "CXCL10 has not been associated with inflammation of peripheral nerves but its possible involvement in the neuropathy associated with T1R deserves further study." (PMID 19473542, 2009). "On Day 2 after injury, at the spinal cord level, increases in CXCL10 and CXCL11 were observed, indicating their role in triggering neuropathy." (PMID 37570736, 2023). "Plasma levels of CXCL9, CXCL10, and CXCL11 have been measured in patients with neuropathy." (PMID 41302503, 2025). "The role of CXCL10 in nociceptive transmission seems to be very important since numerous studies have described its role in this process: its spinal upregulation has already been proven in many animal models, e.g., SNL-, CCI-, CIBP-, and STZ-evoked neuropathy." (PMID 37570736, 2023). "It is known that at the spinal cord level, CXCL10 enhances the amplitude of spontaneous excitatory postsynaptic current and increases NMDA-/AMPA-induced currents via CXCR3; these results support a role for the CXCL10/CXCR3 axis in facilitating excitatory synaptic transmission in neuropathy." (PMID 37570736, 2023). "Furthermore, the serum cytokine profiles of CTS patients were readily distinguishable from those of controls with distinct patterns of the chemokines CCL2, CCL4, CCL5, CXCL8 and CXCL10 and the growth factors VEGF, PDGF and G-CSF, which may be induced by the neuropathy." (PMID 28811623, 2017).
neurosyphilis (9 papers, 2016 to 2026). Infection of the brain or spinal cord by Treponema pallidum. "Above these values CSF CXCL13 was 85.4% sensitive and 89.1% specific for diagnosing neurosyphilis, and CXCL10 and CXCL8 were both 79% sensitive, with a specificity of 90.1% and 91.1%, respectively." (PMID 38983560, 2022). "The mean CXCL10 concentrations were higher in the AH (p<0.01) and CSF (p=0.01) than in the serum of patients with neurosyphilis." (PMID 38983560, 2022). "The AUCs of CSF CXCL13, CXCL8, and CXCL10 were all approximately 0.9 in a previous study, indicating that these chemokines are not only potential biomarkers as complementary diagnostic tools for neurosyphilis but may also be useful for monitoring therapeutic effects." (PMID 32419252, 2020). "CXCL13 and CXCL8/IL-8 have been already studied (individually and in combination with IL-12p40 or CXCL10) in the context of MS and neurosyphilis." (PMID 31356620, 2019). "The CSF/serum ratio of CXCL10 in neurosyphilis patients (median 4.13, ranged from 0.07 to 99.9) was significantly higher than that in non-neurosyphilis patients (median 0.4, ranged from 0.06 to 6.08, p = 0.000)." (PMID 27650493, 2016). "The CSF CXCL10 level in neurosyphilis patients (median 426.55 pg/ml, ranged from 31.2 to 5603.2 pg/ml) were significantly higher than that in non-neurosyphilis patients (median 44.76 pg/ml, ranged from 31.2 to 859.2 pg/ml, p = 0.000)." (PMID 27650493, 2016). "In our study, the levels of CSF CXCL8 and CXCL10 were increased in neurosyphilis patients, especially in symptomatic neurosyphilis patients." (PMID 27650493, 2016). "The area under the ROC curve (AUC) of CSF CXCL13, CXCL8,CXCL10 and the CSF/serum ratio of CXCL13, CXCL8,CXCL10 in the diagnosis of neurosyphilis were 0.940, 0.899, 0.915, 0.963, 0.846 and 0.926, respectively." (PMID 27650493, 2016). "As the diagnostic biomarkers, the AUCs of CSF CXCL10 and CXCL8 levels and the CSF/serum CXCL10 ratio were more than or approximate to 0.9 for all untreated neurosyphilis patients, though they were lower than that of CSF VDRL." (PMID 27650493, 2016). "In conclusion, our data show that CXCL13, CXCL10 and CXCL8 are potential biomarkers to be used as a complementary diagnostic tool for neurosyphilis." (PMID 27650493, 2016). "Elevated concentrations of CXCL8, CXCL10, and IL-10 may also be potential biological markers of neurosyphilis, especially asymptomatic neurosyphilis." (PMID 38105236, 2023). "However, in patients with neurosyphilis, the mean CXCL10 concentrations were higher in the AH (p<0.01) and in the CSF (p=0.01) than the serum." (PMID 38983560, 2022). "Our results suggest that the elevated concentrations of CXCL13, CXCL8, and CXCL10 or their increasing CSF/serum ratios may be potential biomarkers of neurosyphilis, particularly for asymptomatic neurosyphilis." (PMID 27650493, 2016). "The AUC of Model 2 was not statistically different from that of the ratio of CSF/serum CXCL13 and CSF VDRL (p = 0.3968, p = 0.1386, respectively), but it was higher than that of the ratio of CSF/serum CXCL8 and CXCL10 (p < 0.0001, p = 0.007, respectively) for all neurosyphilis." (PMID 27650493, 2016). "The levels of CSF CXCL10 and CXCL8 positively correlated with the CSF-VDRL titer and CSF protein concentration in neurosyphilis patients, indicating that CXCL8 and CXCL10 may be involved in the inflammatory process in neurosyphilis patients." (PMID 27650493, 2016). "CXCL13, CXCL10 and CXCL8 showed AH levels equivalent to previously reported levels in the CSF of patients with neurosyphilis and can potentially be an adjunct in the diagnosis and management of ocular syphilis." (PMID 38983560, 2022). "The sensitivity/specificity of CXCL13, CXCL10, and CXCL8 in the diagnosis of neurosyphilis were 85.4/89.1%, 79/90.1%, and 79.6/91.1%, respectively." (PMID 36452956, 2022). "They found that CXCL13, CXCL10 and CXCL8 levels were significantly increased in the neurosyphilis group." (PMID 38983560, 2022).
neurosyphilis (continued). "The concentrations of CXCL13, CXCL10, and CXCL8 were increased in the CSF of neurosyphilis patients, which was related to the CSF protein concentration and the CSF-VDRL titer." (PMID 36452956, 2022). "In patients with ocular syphilis and neurosyphilis the AH/serum ratios for CXCL13, CXCL10 and CXCL8 were consistently higher than those in patients with ocular syphilis but no neurosyphilis." (PMID 38983560, 2022). "In patients with neurosyphilis, mean AH levels of CXCL13 and CXCL10 were markedly higher than in serum while mean CSF levels of CXCL10 were also markedly higher than in serum." (PMID 38983560, 2022). "The levels of CXCL13, CXCL10 and CXCL8 in the AH of patients with neurosyphilis are similar to previously reported levels in the CSF of patients with neurosyphilis and can potentially be an adjunct in the diagnosis of ocular syphilis." (PMID 38983560, 2022). "The levels of CCL24 (P = .0185), CXCL7 (P < .0001), CXCL13 (P < .0001), CXCL10 (P < .0001), and CXCL8 (P < .0001) in the CSF of neurosyphilis patients were higher than those in the CSF of patients without neurosyphilis." (PMID 32419252, 2020). "Given the measurements were correlated with the disease activity, we therefore investigated the correlation between CSF CXCL13, CXCL10 and CXCL8 levels and these measurements in neurosyphilis patients." (PMID 27650493, 2016). "The AUC of Model 1 was higher than that of CSF CXCL10, CXCL8 for all neurosyphilis (p = 0.0165, p < 0.0001, respectively) and for asymptomatic neurosyphilis (p = 0.0363, p = 0.0047, respectively)." (PMID 27650493, 2016). "The corresponding sensitivities/specificities of CSF CXCL13, CXCL8,CXCL10 and the CSF/serum ratio of CXCL13, CXCL8,CXCL10 in diagnosis of neurosyphilis were 85.4%/89.1%, 79%/90.1% and 79.6%/91.1%, 86.6%/99%, 79%/73.3% and 86%/92.1%, respectively." (PMID 27650493, 2016). "Firstly, it shows that the chemokines measured in the AH of patients with ocular syphilis correlate to the values previously found in the CSF of patients with neurosyphilis, and that patients with ocular syphilis have elevated CSF levels of CXCL13, CXCL10 and CXCL8, as expressed in the mean values." (PMID 38983560, 2022). "In addition, the decrease in the CSF levels of CXCL10 and CXCL8 was consistent with the decrease of CXCL13 levels after treatment for neurosyphilis was initiated." (PMID 38983560, 2022). "Thus, we assessed the efficacy of combined CSF CXCL13, CXCL10 and CXCL8 (Model 1) and combined the ratio of CSF/serum CXCL13, CXCL10 and CXCL8 (Model 2) as biomarkers for diagnosis of neurosyphilis." (PMID 27650493, 2016). "In the search for biomarkers of neurosyphilis, we investigated the chemokine profile in CSF of neurosyphilis patients and found that the concentrations of CXCL13, CXCL10 and CXCL8 were selectively elevated in neurosyphilis patients and correlated with CSF protein concentration and CSF-VDRL titer." (PMID 27650493, 2016). "On the contrary, the serum CXCL10 level was higher in non-neurosyphilis patients than that in neurosyphilis patients, and was also higher in asymptomatic neurosyphilis patients than that in symptomatic neurosyphilis patients (p = 0.003)." (PMID 27650493, 2016). "Given the marked elevation of CSF CXCL13, CXCL10 and CXCL8 as well as CSF/serum ratio of these chemokines in neurosyphilis patients, we further evaluated these chemokines as biomarkers in neurosyphilis diagnosis using the receiver operating characteristic (ROC) curve analysis." (PMID 27650493, 2016). "Also, the AH/serum ratio of CXCL13 and CXCL10, as well as the CSF/serum ratio of CXCL10, was much higher in patients with neurosyphilis than without." (PMID 38983560, 2022). "Similarly, the overall CSF/serum ratio for CXCL10 is 52.45 where for patients without neurosyphilis it is 22.72 and for those with neurosyphilis it is 73.51." (PMID 38983560, 2022).